GNB4 (G protein subunit beta 4)
Description:
Guanine nucleotide-binding proteins (G proteins) are involved as a modulator or transducer in various transmembrane signaling systems. The beta and gamma chains are required for the GTPase activity, for replacement of GDP by GTP, and for G protein-effector interaction.
Synonyms: CMTD1F; HG2B
Tractability: Antibody: the Human Protein Atlas places it where antibodies can reach. PROTAC: ubiquitination databases record sites on it; its protein half-life has been measured.
Gene: Protein-coding gene on chromosome 3 (179,396,088 to 179,451,647, reverse strand). Ensembl gene ENSG00000114450.
Subcellular location (Human Protein Atlas): Plasma membrane; Golgi apparatus
Pathways (Reactome):
Signal Transduction: Ca2+ pathway; Extra-nuclear estrogen signaling; G alpha (12/13) signalling events; G alpha (i) signalling events; G alpha (q) signalling events; G alpha (s) signalling events; G alpha (z) signalling events; G beta:gamma signalling through BTK; G beta:gamma signalling through CDC42; G beta:gamma signalling through PI3Kgamma; G beta:gamma signalling through PLC beta; G-protein activation; GPER1 signaling; Glucagon-type ligand receptors
Hemostasis: ADP signalling through P2Y purinoceptor 1; ADP signalling through P2Y purinoceptor 12; Prostacyclin signalling through prostacyclin receptor; Thrombin signalling through proteinase activated receptors (PARs); Thromboxane signalling through TP receptor
Metabolism: Adrenaline,noradrenaline inhibits insulin secretion; Glucagon signaling in metabolic regulation; Glucagon-like Peptide-1 (GLP1) regulates insulin secretion
Neuronal System: Activation of G protein gated Potassium channels; Inhibition of voltage gated Ca2+ channels via Gbeta/gamma subunits; Presynaptic function of Kainate receptors
Cellular responses to stimuli: High laminar flow shear stress activates signaling by PIEZO1 and PECAM1:CDH5:KDR in endothelial cells
Disease: ADORA2B mediated anti-inflammatory cytokines production
Metabolism of proteins: Cooperation of PDCL (PhLP1) and TRiC/CCT in G-protein beta folding
Transport of small molecules: Vasopressin regulates renal water homeostasis via Aquaporins
Gene Ontology:
Molecular function: protein binding; protein-containing complex binding; signaling receptor complex adaptor activity
Biological process: substantia nigra development; G protein-coupled receptor signaling pathway; signal transduction
Cellular component: extracellular exosome; lysosomal membrane; cytosol; heterotrimeric G-protein complex; synapse
Genetic constraint (gnomAD): Loss-of-function variants: 14 observed, 25.36 expected, observed/expected ratio (o/e) 0.55, 90% interval 0.36 to 0.86. The upper end of that interval is the gene's LOEUF score, 0.86, which puts it in group 3 of 6, group 1 being the genes least tolerant of losing a copy. Missense variants: 227 observed, 314.6 expected, observed/expected ratio (o/e) 0.72, 90% interval 0.65 to 0.81. Synonymous variants: 94 observed, 107.84 expected, observed/expected ratio (o/e) 0.87, 90% interval 0.74 to 1.03.
Gene-disease validity (ClinGen):
ClinGen rates the evidence that GNB4 causes each of these diseases.
Charcot-Marie-Tooth disease (autosomal dominant): Moderate. An inherited degenerative disorder involving the peripheral nerves.
Homologues: Orthologues: chimpanzee GNB4 (100% identical), macaque GNB4 (100% identical), pig GNB4 (100% identical), dog GNB4 (99% identical), rabbit GNB4 (99% identical), guinea pig GNB4 (99% identical), mouse Gnb4 (97% identical), tropical clawed frog gnb4 (95% identical), rat Gnb4 (93% identical), zebrafish gnb4b (91% identical), Caenorhabditis elegans gpb-1 (85% identical), Drosophila melanogaster Gbeta13F (81% identical), and 1 more. Paralogues in human: GNB1 (91% identical), GNB2 (90% identical), GNB3 (80% identical), GNB5 (53% identical).